IL1B (interleukin 1 beta)
Diseases named in the same sentence as IL1B in open-access papers (continued):
Sharing a sentence is not in itself a finding about the gene and the disease.
asthma (429 papers, 2004 to 2026). "In contrast, NA is defined by increased neutrophils in sputum and higher levels of neutrophil-associated cytokines such as IL-1β and IL-8 and is more frequently linked to severe disease, poorer asthma control, and reduced responsiveness to corticosteroids." (PMID 41318536, 2025). "This asthma‐associated composition furthermore correlated with lower levels of topical pro‐inflammatory airway immune mediators (IL‐1β and TNF‐α) and higher levels of monocyte and T‐cell recruiting chemoattractants (CCL‐2 and CCL‐17)." (PMID 39840649, 2025). "The expression of NLRP3 and IL‐1β in sputum has been associated with neutrophilic asthma phenotypes in children, correlating with greater disease severity, poor asthma control, and corticosteroid resistance." (PMID 41318536, 2025). "rs1143643, found in an intron region, has been shown to upregulate serum IL-1β expression and increase asthma risk in children." (PMID 40636929, 2025). "It is reported that IL‐1β can induce liver injury and inflammation in mice, and participate in systemic inflammation caused by asthma." (PMID 39042561, 2024). "For simplicity, this study adopts a dichotomous model where high TGF-β activity in conjunction with IL-1β and IL-6 is linked to asthma, metabolic dysregulations, and an elevated risk of cancer, while it is inversely associated with the occurrence of AR." (PMID 38629073, 2024). "Further studies revealed that azithromycin treatment reduces key sputum cytokines associated with non-T2 asthma, such as IL-6 and IL-1β." (PMID 39194521, 2024). "While IL‐1β can be secreted through various inflammasomes activated by various triggers, the most extensively researched and closely associated with asthma is the NLRP3 inflammasome." (PMID 38668995, 2024). "CXCL1 is one of the most associated hub genes in the pathogenesis of severe asthma, which can be induced by IL-1β, IL-6 and so on." (PMID 38459541, 2024). "IL-1β causes subsequent influx of neutrophils into the airways of mice predisposed by ovalbumin (OVA) induced experimental asthma that is refractory to dexamethasone treatment." (PMID 37759430, 2023). "Elderly people with asthma also exhibit greater sputum cytokines levels, including IL-6 and IL-1β, which were both associated with increased likelihood of hospitalization due to asthma." (PMID 37047327, 2023). "IL1B, a major stimulator of the acute phase response pathway that has been linked to asthma, showed increased gene expression following both TET1 loss and HDM treatment." (PMID 38168374, 2023). "It has been shown that IL-1β levels increase in the serum and sputum of patients with asthma and this increase is associated with the severity of airway dysfunction." (PMID 36945930, 2023). "Sputum neutrophilia in asthma is strongly associated with increased production of several cytokines including IL-1β, IL-6, CXCL8, IL-12, IL-17A and TNF, and this correlates with bacterial burden, in particular Gamma-proteobacteria." (PMID 37180449, 2023). "In terms of inflammatory cytokines, ATG5 was positively associated with TNF-α (rs=0.247, P < 0.001), IL-1β (rs=0.233, P = 0.001), IL-6 (rs=0.213, P = 0.003), and IL-17 (rs=0.154, P = 0.029) in adult asthma patients." (PMID 37644509, 2023). "The pro-inflammatory cytokine IL-1β is associated with decreased lung function, poor asthma control and requirement for high doses of ICS10,45, and its sputum gene expression and protein content are elevated in neutrophilic asthma." (PMID 35013387, 2022). "Single nucleotide polymorphisms (SNPs) in IL1A, IL1B, and IL1R1 are all linked to asthma; accordingly, IL-1α and IL-1β both exacerbate murine allergic airway inflammation." (PMID 35281022, 2022). "Among these, LPS, IL-17, IL-33, CXCL8, C3a/C5a and IL-1β, which have been implicated in various aspects of asthma, are inducers of NET formation in neutrophils." (PMID 34342773, 2022).
asthma (continued). "Previous studies have shown that elevated caspase-1 and IL-1β can be detected in mouse models of asthma, and increased IL-18 can also be detected in the sputum of asthmatic patients and is associated with asthma severity." (PMID 36081945, 2022). "Asthma and allergies in the airways are usually associated with increased mucus production due to the activity of mast cells’ IL-1β and IL-13." (PMID 35266441, 2022). "The stimulation of the NOD-, LRR- and pyrin domain-containing protein 3 (NLRP3) inflammasome and IL-1β synthesis are associated with chronic respiratory diseases such as neutrophil-dominant severe asthma." (PMID 34064821, 2021). "Since IL-1β and TNFα are pro-inflammatory and are associated with macrophage activation and neutrophilic inflammation, their levels are increased in severe asthma and COPD." (PMID 32493287, 2020). "It is therefore unsurprising that IL-1β and some of its downstream targets have been implicated in asthma, particularly in the more severe forms of the disorder." (PMID 32194407, 2020). "With regard to the potential molecular targets of biological therapies for type 2-low neutrophilic asthma, the main focus of current studies is the pathogenic axis connecting IL-1β, IL-23, and IL-17." (PMID 33329598, 2020). "IL-1β has been associated with systemic inflammation in asthma, COPD as well as exacerbations in both the diseases." (PMID 32448302, 2020). "The large quantities of IL-1β produced in the present study are suggestive of the involvement of inflammasomes, which have been linked to asthma severity and steroid resistance." (PMID 32620109, 2020). "Further, experimental human models of asthma exacerbations demonstrate that an early rise in IL-1β in respiratory secretions is temporally associated with clinical symptoms." (PMID 31703379, 2019). "Viral-induced asthma exacerbations, which exhibit both Th1-type neutrophilia and Th2-type inflammation, associate with secretion of Interleukin (IL)-1β." (PMID 29361942, 2018). "The present study involved WT and IL-1β-deficient mice subject to HDM-induced experimental asthma with added viral stimulation-induced exacerbation." (PMID 29361942, 2018). "Up-regulation of the NLRP3 inflammasome and IL-1β has been implicated in asthma in high fat diet (HFD) induced obesity." (PMID 29686414, 2018). "Il1b has been known as a pro-inflammatory cytokine that has been implicated in driving the inflammatory process in various disease states, including asthma." (PMID 27716424, 2016). "Totally, 10 studies met the inclusion criteria and were selected in the meta-analysis with 1,385 cases and 1,964 controls for analysis of the asthma risk and IL-1β -511C/T polymorphism." (PMID 25821855, 2015). "From 1996 to 2013, merging studies have been done to evaluate the association between the IL-1β (-511C/T) and/or IL-1RA polymorphism and asthma risk in different populations." (PMID 25821855, 2015). "We summarized the data on the association between IL-1β -511C/T and IL-1RA polymorphism and risk of asthma in the overall population and performed subgroup analyses by ethnicity, mean of age, and source of controls." (PMID 25821855, 2015). "Accordingly, we conducted a comprehensive meta-analysis to investigate the association between the IL-1β -511C/T and IL-1RA polymorphism and asthma risk." (PMID 25821855, 2015). "A number of studies have investigated the polymorphism of IL-1β -511C/T and IL-1RA genes in relation to asthma susceptibility in different populations." (PMID 25821855, 2015). "Odds ratio (OR) and 95% confidence interval (CI) were used to evaluate the associations between IL-1β -511C/T and IL-1RA polymorphism and asthma risk." (PMID 25821855, 2015). "Logistic regression analysis showed significant associations between genotype and outcome in each of these cases, which remained significant after adjustment for the potential confounders and the association between IL1B and asthma became significant." (PMID 23551418, 2013).
asthma (continued). "Recently, genetic polymorphisms in proinflammatory cytokines such as IL-1β have been recognized as key players in the pathogenesis of asthma." (PMID 22132000, 2012). "In patients with recurrent wheezing induced by RSV and HRV, the expression level of IL-9 are higher.Virus-induced asthma attacks are characterized by an increase in Th1-type neutrophils and Th2-type inflammation, which is associated with the secretion of IL-1β." (PMID 40636260, 2025). "Moreover, steroid resistance in asthma has been strongly associated with neutrophilic inflammation and elevated IL-1β levels, which drive Th17 cell differentiation and IL-17A production, a pathway known to diminish steroid responsiveness." (PMID 41445736, 2025). "Finally, the NLRP3 inflammasome and IL-1β signaling in RV-associated asthma were extensively investigated." (PMID 41011440, 2025). "The mRNA expression of the two evaluated pro-inflammatory cytokines associated with asthma development, namely IL-6 and IL-1β were significantly elevated in the lungs of HDM-challenged mice previously sensitized with HDM and CFA (p < 0.01), when compared to the normal-control animals." (PMID 39129025, 2024). "It has been reported that asthma is associated with a rise in IgE, IL-4, and IL-1β levels." (PMID 37623736, 2023). "IL-1β has recently been implicated in severe asthma and is associated with exacerbations of chronic obstructive pulmonary disease (COPD); however, the underlying mechanisms remain unclear." (PMID 37511021, 2023). "T2-low asthma patients are characterized by sputum neutrophilia secondary to the activation of the NLRP3 inflammasome and elevated IL-1β; the activation of Th1 and/or Th17 cells associated with the imbalance of Th17/Treg cells seems to play an essential role in the pathology of asthma." (PMID 36614301, 2023). "Associations between NTHi and IL-1β are not limited to asthma, with higher levels of IL-1β measured in BAL samples from NTHi+ COPD patients compared to NTHi- COPD patients, as well as increased neutrophils in the airways of COPD patients colonized with H. influenzae." (PMID 35386999, 2021). "Our results suggest that diminished IFN-γ production, as well as overproduction of inflammatory cytokines (IL-1β) in children with asthma, may be involved in their high susceptibility to lower airway symptoms caused by RV infection." (PMID 34220812, 2021). "Also, it was positively correlated with Th1-associated TNF-α, IL-1β and Th17-associated IL-17 to enhance the exacerbation risk of asthma, which showed its potential to regulate Th1 inflammation in asthma." (PMID 33013382, 2020). "IL1B hypersensitivity is a hallmark of the asthma phenotype." (PMID 32571363, 2020). "We hypothesised that IL-1β is causally involved in both Th1 and Th2 features of asthma exacerbations." (PMID 29361942, 2018). "Thus, our data suggest that up-regulation of IL-1β in the lungs is implicated in causality of HFD-induced asthma." (PMID 29686414, 2018). "We suggest that IL-1β signalling pathways may be causally involved in induction of neutrophilic and Th2 features of viral induced asthma exacerbations." (PMID 29361942, 2018). "Considering that a single study may lack the power of providing a reliable conclusion, we performed a meta-analysis to investigate the relationship between the IL-1β (-511C/T) and IL-1RA gene variants and asthma." (PMID 25821855, 2015). "Therefore, further studies are required to clarify the potential gene-gene and/or gene-environment interactions between polymorphisms in the IL-1β -511C/T and IL-1RA gene and asthma." (PMID 25821855, 2015). "Similarly, IL‐1β and IL‐6 are pro‐inflammatory cytokines released by macrophages and dendritic cells and their upregulation have been associated with allergic reactions such as asthma and urticaria." (PMID 34873877, 2022).
asthma (continued). "The production of IL-1β by eosinophils may be a link between the eosinophilic/type-2 immune response and the neutrophilic/type-17 immune response that is often associated with a more severe and treatment-refractory type of asthma." (PMID 30906226, 2019). "This asthma-associated composition furthermore correlated with lower levels of topical pro-inflammatory airway immune mediators (IL-1β and TNF-α), which may characterize an inefficient anti-bacterial response, and higher levels of monocyte and T-cell recruiting chemoattractants (CCL2 and CCL17)." (PMID 31676759, 2019). "Interestingly, previous studies reported ERK phosphorylation in airway smooth muscle cells that cause increased production of both IL-1β and granulocyte-macrophage colony-stimulating factor, which are involved in the contractile response and remodeling of the airways in asthma." (PMID 25329458, 2014). "Interleukin-1β (IL-1β) is a key mediator of innate immunity and a central driver of airway inflammation in asthma and chronic obstructive pulmonary disease (COPD)." (PMID 42168720, 2026). "Recently, it was observed that luteolin alleviates the inflammatory responses and secretions of inflammatory factors in human bronchial epithelial cells during asthma by inhibiting IL‐1β and MAPK signaling and reduced the secretion of IL‐36γ." (PMID 39830909, 2025). "Additional findings implicate inflammasome‐related cytokines (IL‐1β, IL‐18) in neutrophilic asthma phenotypes, poor asthma control, and corticosteroid resistance in pediatric disease." (PMID 41318536, 2025). "In a mouse model of obesity‐associated asthma, airway hyperreactivity—a cardinal feature of asthma—was dependent on IL‐17 producing ILC3s that were activated by macrophage‐derived IL‐1β." (PMID 40016948, 2025). "Our molecular docking confirmed interactions of these active components, particularly Kaempferol and Norephedrine, with core targets AKT1, TNF, and IL1B, underscoring their potential therapeutic roles in managing asthma." (PMID 40420184, 2025). "This process is functionally essential for asthma, since the inhibition of IL-1β can modulate the Th17/Treg immunological imbalance and reduce neutrophil-driven airway inflammation in an ovalbumin-induced asthma model." (PMID 41008562, 2025). "Viral infections, another well-known trigger of asthma, have also been shown to increase the release of IL-25, IL-33 and IL-1β from epithelial cells." (PMID 39962262, 2025). "The ability of mefenamic acid to inhibit the NLRP3 inflammasome offers additional therapeutic potential by decreasing the airway inflammation mediated by IL-1β, a key cytokine involved in severe asthma." (PMID 40851698, 2025). "A 2024 cross‐sectional study demonstrated significantly elevated levels of NLRP3, IL‐1β, and IL‐6 in children with asthma compared to healthy controls, with the highest levels observed in those with moderate to severe disease." (PMID 41318536, 2025). "For instance, IL-1β plays a role in the severity of conditions like AD, asthma, and allergic rhinitis, as well as in the immune dysregulation leading to food allergies." (PMID 39860604, 2025). "NLRP3 and IL-1β inhibition in mice infected with RV resulted in an asthma-like phenotype, including increased mucus production and type 2 inflammation in immature mice compared to mature mice." (PMID 41011440, 2025). "For instance, outer membrane vesicles (OMVs) from NTHi have been shown to increase the secretion of interleukin (IL)-1β and IL-17, contributing to neutrophilic inflammation in asthma." (PMID 40871268, 2025). "In serum and BALF, IL-1β expression increased significantly in the asthma group compared with the control group." (PMID 38273268, 2024).
asthma (continued). "Treatment with miR-223 agomirs in neutrophilic asthmatic mouse models attenuates airway inflammation, reduces NLRP3 levels, and decreases IL-1β release, suggesting miR-223 as a potential therapeutic candidate for severe non-T2 asthma." (PMID 39554494, 2024). "In summary, high TGF-β levels in asthma compared to AR, and high IL-1β levels in neutrophilic asthma compared to eosinophilic asthma promote a Th17 related pro-inflammatory environment in asthmatic patients especially in patients with neutrophilia." (PMID 38629073, 2024). "In patients with asthma, increased IL-6 and IL-1β levels are markers for systemic inflammation and are associated with reduced forced expiratory volume in 1 second (FEV1) and elevated acute exacerbations." (PMID 39439788, 2024). "In a randomized, double-blind, placebo-controlled trial assessing oligo-fucoidan’s role in asthma patients, it lowered serum IL-1b and IL-6 after 4 weeks and significantly reduced serum IL-8 after 24 weeks." (PMID 39728104, 2024). "Neutrophilic asthma patients showed a marked increase in caspase-4 expression and elevated production of IL-1β and IL-18." (PMID 39795884, 2024). "Collectively, the distinct association of asthma with long-term comorbidities can be primarily attributed to neutrophilic patients, due to the elevated circulatory levels of TGF-β, IL-1β and IL-6 in this type of asthma." (PMID 38629073, 2024). "A cohort of 240 subjects (6 to 10 years old) with PAR (PAR alone: 113 children, PAR and asthma: 127 children) was analyzed for various biomarkers, including IL-1β, iNOS, and epithelial-mesenchymal transition (EMT) markers in serum." (PMID 38167134, 2024). "IL-1β is a regulator of airway hyperresponsiveness in asthma and can mediate eosinophil inflammation by inducing chemokines and cytokines." (PMID 38218943, 2024). "Considering the interactions between IL‐1β and other cytokines would provide a more effective treatments for severe asthma." (PMID 38668995, 2024). "In the univariate analysis, IL-1β (> 10.84 pg/ml), iNOS (> 43.63 pg/ml), and vimentin (> 486.0 pg/ml) were associated with the development of comorbidity of PAR and asthma (p = 0.003, 0.038 and 0.005, respectively)." (PMID 38167134, 2024). "In this study, we observed that children with higher IL-1β levels faced increased risks of AR and asthma comorbidity and decreased lung function." (PMID 38167134, 2024). "Blockade of IL-1β modulated Th17/Treg immune imbalance and attenuated neutrophil airway inflammation in an ovalbumin-induced mouse model of asthma." (PMID 39108751, 2024). "Commercially available drugs that target IL-1, including anakinra, a recombinant human IL-1 receptor antagonist, and canakinumab, a human monoclonal antibody targeting IL-1β, have been investigated in the treatment of asthma." (PMID 39194521, 2024). "We demonstrated that N-GSDMD, IL-18, and IL-1β were significantly increased in samples with mild asthma compared with those from the controls." (PMID 38849380, 2024). "We observed that the expression of N-GSDMD, IL-18, and IL-1β was enhanced in OVA-induced asthma mouse model." (PMID 38849380, 2024). "The airways of individuals with severe asthma have more elastin compared to healthy controls due to the effects of TNFα, IL-1β, and TGFβ on myofibroblasts." (PMID 39194521, 2024). "ELISA was used to measure concentrations of cytokines (IL-1β, IL-18, IL-17A, and IL-10) in serum samples collected from asthma patients and healthy individuals." (PMID 38849380, 2024). "Secondly, our study primarily focused on identifying new substances that inhibit the secretion of IL‐1β through NLRP3 in severe asthma." (PMID 38668995, 2024). "This study investigated the role of interleukin-1β (IL-1β), a pro-inflammatory cytokine, and inducible nitric oxide synthase (iNOS) in the comorbidity of AR and asthma and lung function in Korean children with perennial AR (PAR)." (PMID 38167134, 2024).